EZH2 (enhancer of zeste 2 polycomb repressive complex 2 subunit)
Diseases named in the same sentence as EZH2 in open-access papers (continued):
Sharing a sentence is not in itself a finding about the gene and the disease.
ovarian carcinoma (continued). "There is mounting evidence that up-regulation of EZH2 occurs in ovarian carcinoma, and is positively correlated with worsening histological grade and advanced stage." (PMID 30064416, 2018). "The EZH2 blockade by RNA interruption hampers the proliferation of the ovarian cancer through the facilitation of re-expression of p2130,31." (PMID 29970899, 2018). "Inhibition of EZH2 methytransferase increases chemokine production and improves T cell infiltration in patients with ovarian cancers." (PMID 30740111, 2018). "In two independent murine models of orthotopic ovarian carcinoma, established by injection of HeyA8 or SKOV3ip1 cells human ovarian carcinoma cell lines, siRNA-mediated inhibition of human EZH2 led to only a mild tumor inhibition." (PMID 30103412, 2018). "In an orthotopic model of ovarian carcinoma, treatment with chitosan NPs carrying siRNAs targeting human EZH2 (expressed in the transplanted cancer cells) or murine EZH2 (expressed in the endogenous murine vasculature) inhibited tumor growth." (PMID 29670528, 2018). "EZH2 promotes the ability for invasion and metastasis of ovarian carcinoma cells by regulating TGF-β1." (PMID 30064416, 2018). "In conclusion, we describe a set of genes overexpressed in ovarian cancer with potential for therapeutic intervention including EZH2 and UBE2C." (PMID 29575713, 2018). "The percentage of EZH2+ CD8+ T cells in ovarian cancer tissues is a stronger predictor of overall and progression-free survival as compared to the percentage of CD8+ T cells." (PMID 29556394, 2018). "Recent work has indicated that cancer-associated fibroblasts (CAFs) have an ability to enhance the growth and invasion of ovarian cancer cells, and this ability is partly due to increasing EZH2 expression." (PMID 30064416, 2018). "EZH2 is thought to be an independent forecaster of poor overall survival for women with ovarian carcinoma." (PMID 30064416, 2018). "Inhibition of EZH2 in tumor-specific T cells increases the tumor burden and the metastatic potential in mice models of ovarian cancer." (PMID 29556394, 2018). "3-Deazaneplanocin A (DZNEP), the first indirect inhibitor of EZH2, was reported to be a promising cancer-fighting agent for malignant ovarian tumor, with potential to reduce proliferation, induce apoptosis, and inhibit metastasis." (PMID 30064416, 2018). "EZH2 downregulation in ovarian cancer has been shown to sensitize tumor cells to cisplatin and EZH2 overexpression is associated with resistance to cisplatin through H3K27 tri-methylation of drug-resistance genes." (PMID 29093822, 2017). "EZH2 facilitates epigenetic methylation to modulate gene expression, and both uterine and ovarian cancers show evidence of EZH2 over expression." (PMID 29093822, 2017). "In fact, in ovarian cancer cells, EZH2 was found to regulate TGF-β1 expression and facilitate invasiveness and metastasis." (PMID 28754964, 2017). "In conclusion, EZH2 promotes ovarian cancer migration and invasion via the epigenetic silencing of TIMP2 by H3K27me3 and DNA hypermethylation, which leads to the activation of MMP2 and MMP9." (PMID 28620234, 2017). "EZH2 plays an integral role in cellular proliferation, apoptosis and invasion in human epithelial ovarian cancer cell lines (." (PMID 29093822, 2017). "For example, miR-212 was down-regulated in ovarian cancer, potentially due to the significant enrichment of EZH2 and H3K27me3 in the promoter region." (PMID 28594854, 2017). "In support, overexpression of Ezh2 is shown to increase recruitment of Dnmts at the TIMP2 promoter in ovarian cancer." (PMID 29261844, 2017). "EZH2 overexpression is found in 50–85% of ovarian carcinomas, with high expression correlating with high grade, more advanced stage disease and poor survival." (PMID 29093822, 2017). "We found that both EZH2 mRNA and protein levels were up-regulated in ovarian cancer compared with normal tissue." (PMID 28620234, 2017).
ovarian carcinoma (continued). "In the present study, bioinformatics analysis of RNA sequencing microarray data confirmed the high EZH2 expression in ovarian cancer and its correlation with metastasis and poor patient survival." (PMID 28620234, 2017). "This underlines the need for a selective approach that takes into account the lncRNAs present in a given model and/or tumor before considering EZH2 as a potential therapeutic target in ovarian carcinoma." (PMID 26992233, 2016). "Here we report the functional roles of EZH2-catalyzed H3K27me3 during EMT in ovarian cancer (OC) cells." (PMID 27563817, 2016). "EZH2 knockdown in ovarian cancer cell lines led to reduced cell proliferation and inhibited cell migration and/or invasion in vitro." (PMID 26992233, 2016). "Specifically, the promoter of BMAL1 is trimethylated on histone H3 at lysine 27 by enhancer of Zeste homolog 2 (EZH2) in ovarian cancer CP70 and MCP2 cells." (PMID 26253128, 2015). "Previous studies have indicated that (EZH2) is involved in resistance of ovarian cancer cells to platinum-based drugs, such as cisplatin, carboplatin and paclitaxel." (PMID 25955318, 2015). "The present study further investigated EZH2 and found that it was downregulated in cisplatin-sensitive ovarian cancer cells." (PMID 25955318, 2015). "The miR-101 negatively regulates EZH2 in ovarian cancer cell lines, and miR-101 over-expression resulted in decreased cellular proliferation and migration." (PMID 26633386, 2015). "The first clue on a possible role of EZH2 in tumor angiogenesis came from a report about ovarian carcinoma in 2010, which identified EZH2 as a key regulator of tumor angiogenesis." (PMID 25237831, 2014). "Additional analysis of the TCGA ovarian cancer dataset demonstrates that ovarian cancer patients with low expression of EZH2, a polycomb-group family protein, show positive correlation between E2F6 and c-KIT." (PMID 25545504, 2014). "EZH2 caused VASH1 silencing by promoter methylation and subsequently promoted angiogenesis in ovarian cancer." (PMID 25237831, 2014). "Emerging evidence has shown that EZH2 is a key regulator of cancer angiogenesis in ovarian cancer, glioblastoma, Kaposi sarcoma and bladder cancer." (PMID 25237831, 2014). "EZH2 knock-down leads to decreased ovarian cancer stem cell population and a re-acquisition of chemo-sensitivity." (PMID 25431950, 2014). "We conjecture that a simultaneous EZH2 inhibition and anti-estrogen therapy can constitute an effective combined therapeutic strategy against ovarian cancer." (PMID 25545504, 2014). "Down-regulation of EZH2 in these stem cell-like populations in ovarian cancer cell models reduced anchorage-independent growth and tumor growth in vivo." (PMID 24971229, 2014). "High expression of EZH2 is seen in ovarian cancer, correlating with advanced stage and is a predictor of poor survival." (PMID 24971229, 2014). "Our recent studies have shown that the three-dimensional culture sensitizes epithelial ovarian cancer cells to EZH2 methyltransferase inhibition, which suppresses cell growth, induces apoptosis and inhibits invasion." (PMID 24294976, 2013). "Expression of two cyclin-dependent kinase (CDK) inhibitors CDKN1A/p21 and CDKN1C/p57 were also demonstrated to be regulated by EZH2 in cervical and ovarian cancer, respectively." (PMID 23599754, 2013). "Combined, these data provide a significant conceptual advance in our understanding of the regulation of angiogenesis in ovarian carcinoma, and support the potential for targeting ezh2 as a therapeutic approach." (PMID 23109879, 2012). "A similarpattern was observed for EZH2 although expression in ovarian cancer was similarto fallopian tube epithelium." (PMID 21423607, 2011). "Taken together, this study establishes the first potential evidence that EZH2 inhibition may reprogram eccDNA dynamics to potentially restore SFRP1 tumor suppressor expression in ovarian cancer." (PMID 41744650, 2026).
ovarian carcinoma (continued). "One study found that miR-101 and miR-26a may target the enhancer of the zeste homolog 2 (EZH2)-Notch signaling pathway and decrease T cell aerobic glycolysis, thereby reducing tumorigenesis in ovarian cancer." (PMID 39007129, 2024). "Some preclinical data suggest that inhibition of EZH2 may be effective in ovarian cancer, and mechanistically, inhibition of EZH2 histone methyltransferase activity is synthetically lethal in ARID1A mutant cancers." (PMID 39697230, 2024). "EZH2 is gaining attention as an attractive therapeutic target for ovarian cancer." (PMID 37210576, 2023). "Herein, our data indicate that CHD4 cooperates with EZH2 in ovarian cancer to exert its key roles and that these roles may be mediated in part by Wnt/β-catenin pathway activation." (PMID 36681835, 2023). "To explore whether EZH2 is necessary for the inhibitory effect of CHD4 on ovarian cancer, we overexpressed EZH2 in a CHD4 knockdown OC cell line." (PMID 36681835, 2023). "The clinical significance of EZH2 prompted us to experimentally assess whether CHD4 and EZH2 are correlated in ovarian cancer." (PMID 36681835, 2023). "exhibited that the hsa_circ_0026123/miR-124-3p/EZH2 axis could play critical role in ovarian cancer." (PMID 37559140, 2023). "Indeed, dual inhibition of both EZH2 and EHMTs are a novel avenue for drug development in ovarian cancer." (PMID 37853473, 2023). "For this purpose, we examined the EZH2 protein level in CHD4 knockdown ovarian cancer cells." (PMID 36681835, 2023). "However, EZH2 inhibitors still have limited efficacy in some tumors with high expression of EZH2, such as ovarian cancer, which calls for deeper exploration of new drug combination schemes." (PMID 36263120, 2022). "However, a separate study found that EZH2 inhibition slowed ovarian cancer cell growth in culture in a dose-dependent manner." (PMID 36359771, 2022). "For instance, EZH2 knockdown upregulated the expression of E-cadherin in ovarian cancer cells." (PMID 36316365, 2022). "It is noteworthy that miRNA-34c inhibits EZH2 in favor of reducing ovarian cancer proliferation." (PMID 35236381, 2022). "Both miRNAs and EZH2 demonstrate abnormal expressions in ovarian cancer." (PMID 35236381, 2022). "They suggested that repression of endoribonuclease Dicer, which is an EZH2 target in the cisplatin-resistant A2780 ovarian cancer cell line, could be among the potential mediators of cisplatin resistance." (PMID 36230683, 2022). "Similarly, low EZH2 and H3K27me3 levels are predictors of better chemotherapy outcomes in ovarian cancer." (PMID 35203421, 2022). "Indeed, the miRNA/EZH2 interaction determines progression and chemoresistance of ovarian cancer cells." (PMID 35236381, 2022). "However, when all stages are lumped together, higher EZH2 expression in high-grade epithelial ovarian cancer correlates with mortality." (PMID 36359771, 2022). "Indeed, epigenetic therapy targeting EZH2 can not only suppress cancer stemness but also restore anti-tumor immune response in ovarian cancer." (PMID 35216394, 2022). "Moreover, in T cells, researchers discovered that EZH2 transcription is regulated via anaerobic glycolysis metabolism through miRNAs, rendering it functional and therapeutically crucial in ovarian cancer patients." (PMID 36483029, 2022). "Additionally, EZH2 can be considered as a prognostic factor, so that low expression of EZH2 leads to a good prognosis and improve progression-free survival rate of ovarian cancer patients." (PMID 35236381, 2022). "We observed a significantly extended survival of mice treated with HKMTI-1–005, indicating that G9A/EZH2 inhibition may provide a useful tool to overcome the poor immune reaction to ovarian cancer in patients." (PMID 35131874, 2022). "Furthermore, in T cells, it has been found that enhancer of zeste homolog 2 (EZH2) expression is controlled via glycolytic metabolism through miRNAs in patients with ovarian cancer." (PMID 36483029, 2022).
ovarian carcinoma (continued). "Another study showed that the expression of EZH2 was positively correlated with c-KIT (CD117), a surface marker of EOCSCs, and that EZH2 inhibition may represent an effective therapeutic strategy against ovarian cancer." (PMID 33408782, 2021). "Noteworthy, several histone methylation modifiers have been related to miRNA regulation, such as EZH2 in ovarian cancer, which has been shown to induce the repressive histone mark H3K27me3 in target miRNAs: miR-101-3p, let-7e-5p, miR-26a-5p, miR-98-5p, and miR-141-3p." (PMID 34298969, 2021). "Interestingly, we also observed that EZH2 protein in platinum resistant tumors was negatively correlated with HDAC7 which is transcriptionally upregulated in ovarian cancer stem cells." (PMID 34140011, 2021). "In ovarian cancer, EZH2 could retain cell stemness and confer chemoresistance by promoting CHK1 signaling." (PMID 34992654, 2021). "To further confirm the roles of AURKA and EZH2 in the cell cycle pathway of cancer stem cells, we analyzed single-cell RNA-seq datasets of ovarian carcinoma in the CancerSCEM database (Cancer Single-cell Expression Map database) based on the E-MTAB-8559 dataset." (PMID 35059393, 2021). "Paradoxically, in ovarian cancer models, EZH2 inhibition has nothing to do with the alteration of the class I antigen presentation of ovarian cancer cells, indicating that the regulation of EZH2 on antigen presentation may be cancer-type specific." (PMID 35003090, 2021). "It has been further verified that the estrogen-mediated E2F6-miR-193a-EZH2 network could promote stemness of ovarian cancer cells via in vitro and in vivo experiments." (PMID 34122542, 2021). "Moreover, EZH2 inhibition was recently shown to shift repair from HR to NHEJ in some ovarian cancer cell lines." (PMID 34745220, 2021). "The most frequent EZH2 amplification (11.4%) was observed in ovarian cancer." (PMID 34202528, 2021). "Finally, in clinical samples, ovarian cancer patients with high levels of EZH2 and CHK1 not only were more resistant to platinum but also had a poorer prognosis." (PMID 33408782, 2021). "Pharmacological EZH2 inhibition in vivo also led to increased levels of tumor-producing pro-Th1 chemokines and enhanced recruitment of effector T cells, resulting in reduced tumor volume and prolonged survival time in human ovarian cancers." (PMID 34737746, 2021). "Conversely, knockdown of EZH2 re-sensitizes drug-resistant ovarian cancer cells to cisplatin." (PMID 34140011, 2021). "EZH2 overexpression/amplification has been widely reported in ovarian cancers." (PMID 34213777, 2021). "Similarly, our study not only identified that EZH2 is a direct regulator of CHK1 expression in ovarian cancer but also demonstrated that CHK1 signal activation is required for EZH2-dependent CSC expansion and maintenance." (PMID 33408782, 2021). "In addition, EZH2 was also shown to play a unique role in activating rather than repressing CHK1 signaling through binding to the CHK1 promoter in epithelial ovarian cancer cells." (PMID 33408782, 2021). "Likewise, a similar KDM2B-H3K4me3-mediated EZH2 upregulation has been found in ovarian cancer cells." (PMID 34266408, 2021). "EZH2 and BAF155 have been reported to co-regulate tumor suppressor genes, and inhibiting BAF155 methylation could lead to displacement of BAF155 by EZH2 in ovarian cancer." (PMID 34865122, 2021). "EZH2 is involved in ovarian cancer although multifaceted roles likely exist, so whether it is acting as a tumour suppressor or oncogene is unclear and may be context dependent." (PMID 33669182, 2021). "However, knockdown of EZH2 levels also correlate with an induction of apoptosis in epithelial ovarian cancer cells, and regression of tumour xenografts." (PMID 33669182, 2021). "In patients with ovarian cancer, high rate of EZH2+ CD8+ T cells positively affect cancer survival." (PMID 34737746, 2021).
ovarian carcinoma (continued). "Interestingly, miR-137 mediated the functional link between c-MYC and EZH2, regulating cisplatin resistance in ovarian cancer." (PMID 34298969, 2021). "Besides, EZH2/H3K27Me3 and phosphorylated EZH2 were reported to predict chemotherapy response and prognosis in ovarian cancer." (PMID 33292225, 2020). "Above all, the rescue experiments demonstrated that the function of EZH2 in ovarian cancer might be dependent on the expression of CYP27B1." (PMID 33163485, 2020). "In the present study, our data showed that CYP27B1 was upregulated after the knockout of the oncogene EZH2, which may reduce the level of H3K27me3 in ovarian cancer cells; this finding was also consistent with previous data." (PMID 33163485, 2020). "However, the biological effects and molecular mechanism of EZH2 in ovarian cancer are still unclear." (PMID 33163485, 2020). "In ovarian cancer, EZH2 upregulation has been widely established." (PMID 33763107, 2020). "We proposed that a similar feedback may exist in ovarian cancer to maintain the high expression of EZH2." (PMID 33718109, 2020). "The levels of EZH2 negatively correlated with intratumoral CD8+ T cells in ovarian cancer, so EZH2 inhibitor could increase effector T cell tumor infiltration, slowed down tumor progression, and synergistically improved the efficacy of adoptive T cell therapy." (PMID 32723346, 2020). "Enhancer of zeste homolog 2 (EZH2) is a major tumor marker and an effective therapeutic target for ovarian cancer, but the underlying molecular mechanism remains unclear." (PMID 33163485, 2020). "In addition, treating human ovarian cancer-specific T cells with an EZH2 inhibitor prior to adoptive transfer led to increased tumor growth in a humanized ovarian cancer mouse model." (PMID 32367803, 2020). "The high prevalence of SWI/SNF mutations in various human malignancies, the occurrence of SMARCA4 as the driver mutation in SCCOHT and the potential therapeutic strategy of EZH2 inhibitors led us to explore the role of SMARCA4 and EZH2 in epithelial ovarian cancers." (PMID 33230143, 2020). "Moreover, it is reported that NF-YA is a key regulator of EZH2 expression in ovarian cancer, and it is required for cell proliferation." (PMID 33163485, 2020). "EZH2 inhibited these proliferation-related genes to promote the proliferation of ovarian cancer." (PMID 33718109, 2020). "Moreover, we performed RIP assays and found that LINC00511 directly bound with EZH2 in ovarian cancer cells." (PMID 31016892, 2019). "In this study, we found that LINC00511 could bind with histone trimethyltransferase EZH2 in ovarian cancer cells." (PMID 31016892, 2019). "At present, the nature of signals which might be contributing to increased EZH2 expression in ovarian cancer remains unknown." (PMID 31426393, 2019). "Moreover, EZH2 and KDM6B were frequently both overexpressed and associated with EMT, invasion, migration, or metastasis in the same cancer types, such as ovarian cancers or clear cell renal cell carcinomas." (PMID 34991274, 2018). "Some of the identified genes such as EZH2 or UBE2C have not been described previously in ovarian cancer but are amplified, linked with detrimental prognosis and potentially druggable, and warrant preclinical and clinical assessment." (PMID 29575713, 2018). "A recent study using mouse models of ovarian cancer has shown that the reduced production of CXCL9 and CXCL10 from cancer cells is caused by enhancer of zeste homolog 2 (EZH2) mediated histone modification and DNA methyltransferase 1 (DNMT1) mediated DNA methylation of the chemokine genes." (PMID 30483271, 2018). "Here, we report that EZH2 inhibition is effective in CARM1-expressing epithelial ovarian cancer." (PMID 29434212, 2018). "Similarly, it has been suggested, in the ovarian cancer cell line HO-8910, that EZH2 repressed CDH1 gene expression." (PMID 34991274, 2018).